TLR9 (toll like receptor 9)
Diseases named in the same sentence as TLR9 in open-access papers (continued):
Sharing a sentence is not in itself a finding about the gene and the disease.
HCMV infection (continued). "A polygenic score including the TLR4 (rs4986790/rs4986791), TLR9 (rs3775291), TLR3 (rs3775296), AIM2 (rs855873), TLR7 (rs179008), MBL (OO/OA/XAO), IFNL3/IL28B (rs12979860) and IFI16 (rs6940) SNPs was built based on the risk of CMV infection and disease." (PMID 36016941, 2022). "Regarding the HCMV infection, previous papers showed some contribution of TLR9 to its occurrence." (PMID 28340580, 2017). "The research was aimed to estimate the role of three single nucleotide polymorphisms (SNPs) located in TLR2 gene, and the common contribution of TLR2, and previously studied TLR4 and TLR9 SNPs, to the occurrence of congenital HCMV infection in fetuses and newborns." (PMID 28118851, 2017). "Therefore, the current paper was aimed to describe the role of TLR2, TLR4 and TLR9 SNPs in the occurrence of HCMV infection among pregnant women, acquired within the gestation period." (PMID 28340580, 2017). "However, we suggest that further detailed studies would highly be justified to investigate the molecular mechanism of the TLR9 2848 G > A SNP function in HCMV infection." (PMID 28340580, 2017). "The distinct contribution of the analyzed TLR9 SNP in the occurrence of HCMV infection may have been age-related, as well as may have resulted from the classification bias." (PMID 28340580, 2017). "On the other hand, the TLR9 2848 G > A polymorphism was not involved in the incidence of HCMV infection among the examined patients." (PMID 28340580, 2017). "We speculate that genetic variations of TLR9 that down regulate its expression could reduce the function of the innate immune response against HCMV infection." (PMID 27105145, 2016). "Statistically significant differences between infants with and without HCMV infection were observed for the TLR9 -1486T/C, 1174G/A, and 2848C/T polymorphisms." (PMID 27105145, 2016). "However, other studies showed some role of SNPs in TLR2, TLR3, TLR4, TLR7 and TLR9 genes in HCMV infections." (PMID 25844529, 2015). "TLR3 and TLR9 levels were increased after 1 hr of HCMV infection." (PMID 23061052, 2012). "It was demonstrated that HCMV infection strongly induced TLR9 expression in fibroblast." (PMID 20696081, 2010). "Mouse TLR9 plays a role in defense against systemic mouse cytomegalovirus infection." (PMID 17517123, 2007). "Likewise, TLR9 variants (T/C, rs187084; C/T, rs352140) are associated with CMV disease in children and TLR2 variants (A>G, rs5743708) are associated with increased risk of congenital HCMV infection in a Polish cohort." (PMID 36016941, 2022). "The distribution of allele frequencies of TLR9 SNPs in infants with and without HCMV infection." (PMID 27105145, 2016). "Notably, the stimulation of TLR9 by its ligand, CpG-B, when added after viral entry, enhances HCMV infection in fibroblasts by an unknown mechanism, suggesting that the virus exploits TLR9 signaling to further its replication during infection of stromal cells." (PMID 22701276, 2012). "The role of TLR SNPs in congenital and acquired HCMV infection was reported for TLR2, TLR3, TLR4, TLR7, and TLR9 SNPs in various populations." (PMID 34578364, 2021). "TLR2, TRL3, and TLR9 were determined as inducing the expressions of IFN-β and tumor necrosis factor alpha (TNF-α) at early times during HCMV infection in human THP-1 cells, as well as in human foreskin fibroblasts (HFF)." (PMID 30241345, 2018). "Both TLR3 and TLR4 were correlated with the inhibition of HCMV infection in HFF and cervical tissue, while TRL2 and TLR9 also induced HCMV inhibition in ectocervical explants." (PMID 30241345, 2018). "Fifty-nine cases of HCMV infection and part of uninfected subjects has been described previously in detail for TLR2, TLR4, and TLR9 SNPs." (PMID 28046022, 2017). "In ectocervical tissue, HCMV infection was blocked by ligands for TLR2 (LTA), as well as TLR9 (CpG) molecules." (PMID 28118851, 2017).
HCMV infection (continued). "In human acute monocytic leukemia cell line THP1 and in foreskin fibroblast cell lines, HCMV infection induces the expression of TLR2, TLR3 and TLR9 genes." (PMID 28118851, 2017). "Despite the rather small number of studies on the relationship between TLR9 2848 SNP and congenital infection with HCMV, a number of reports inform that the contribution of TLR9 to the occurrence and development of HCMV infections is available." (PMID 25844529, 2015). "Recently, HCMV infection has been shown to result in upregulation of TLR2, TLR3, and TLR9 in monocytes in the presence of the human monocyte scavenger receptor A type 1 (SR-A1)." (PMID 23061052, 2012). "Our recent study in fetuses and neonates, with and without congenital HCMV infection, presented that TLR4 and TLR9 SNPs were associated with the development of congenital cytomegaly." (PMID 28118851, 2017). "Therefore, the common contribution of TLR9 2848 G>A, together with TLR2 2258 G>A SNP, to the occurrence of HCMV infection seems possible." (PMID 28118851, 2017). "In the group of infants without HCMV infection, the frequencies of genotypes at all TLR9 SNPs were in HWE (P > 0.05)." (PMID 27105145, 2016). "Other TLRs that play a role in resistance to CMV infection are TLR3 and TLR9." (PMID 25856589, 2015). "It has been reported that TLR9 stimulation plays both positive and negative roles in HCMV infection and that TLR4 and TLR9 activation can increase gene expression from a human CMV enhancer expression plasmid." (PMID 25856589, 2015). "Although pDC expressed particularly high levels of cGAS, and the cGAS/STING axis was functional down-stream of STING, as indicated by IFN-I induction upon synthetic cGAMP treatment, pDC were not susceptible to HCMV infection and mounted IFN-I responses in a TLR9-dependent manner." (PMID 27058035, 2016).
colon carcinoma (19 papers, 2012 to 2025). "CpG-C, a TLR-9 agonist, also markedly improved resistance to colon cancer-associated hepatic metastases in postoperative mice." (PMID 33672617, 2021). "Toll-like receptor 9 (TLR9) in colon cancer cells binds extracellular DNA in vitro and is capable to promote tumor survival and progression through induction of autophagy." (PMID 38419052, 2024). "In this study, we investigated the immunotherapeutic effects of ADU-S100 as a STING agonist and CpG ODN1826 as a TLR9 agonist in a preclinical model of colon carcinoma." (PMID 37901237, 2023). "The results illustrate the potential of targeting the STING and TLR9 pathways as powerful immunoadjuvants in the treatment of preclinical colon carcinoma and the possibility of harnessing these pathways in future therapeutic approaches." (PMID 37901237, 2023). "In HT29 colon cancer cells, a close interplay between self-DNA-induced TLR9-signaling and autophagy response was found with notable effects on cell survival and differentiation." (PMID 35551547, 2022). "By adding colon cancer cell-derived cfDNA or the TLR9 agonist CpG-ODN2395 to CRC cell lines, researchers found that the TLR9-MyD88 signaling boosted cell growth, migration, invasion, and IL8 secretion." (PMID 36359370, 2022). "In colon carcinoma, activation of TLR9 has been shown to favor survival and chemotherapy resistance of tumor cells." (PMID 25846753, 2015). "HT29 colon carcinoma cells also express TLR9 that can be activated by pathogen-originated DNA sequences." (PMID 24459426, 2013). "Many reports have demonstrated that NETs could upregulate TLR9 expression in colon cancer cells and that TLR is an upstream regulator of COX2 expression." (PMID 31907001, 2020). "Moreover, TLR9 agonists were shown to inhibit colon cancer cell proliferation, promote apoptosis, and improve the beneficial effects of radiotherapy." (PMID 28632155, 2017). "Furthermore, modulation of TLR9 in WT mice reconstituted with IL-23p19−/− bone marrow cells strongly enhanced the protection against colon tumors and chronic inflammation." (PMID 28191009, 2017). "In addition, TLR9 exhibits also anti-tumoral activity in a xenograft model of colon cancer." (PMID 28632155, 2017). "In summary, in this study we aimed to assess the complex interaction of HGFR, TLR9 signaling and autophagy inhibition on the survival and proliferation of HT29 colon cancer cells upon modified tumorous self-DNA treatments." (PMID 35551547, 2022). "In our study, we attempted to answer how IGF1R inhibition modulates the effect of tumor-derived self-DNA on TLR9 signaling and autophagy response by examining the metabolic activity and proliferation of HT29 colon cancer cells." (PMID 35651701, 2022). "Immunogenically dying CT26 colon carcinoma cells killed by MTO in vitro and adorned with CpG nanoparticles (adjuvant TLR9-agonist) have been already shown to foster maturation of DCs, T cell responses and antitumor responses in mouse models." (PMID 32992645, 2020). "Beyond immune cells, recent data suggests that TLR9 expression can also be detected in various normal and tumorous cells, including HT29 colon carcinoma cells." (PMID 24459426, 2013). "Ex vivo studies in MC38 colon cancer cell lines and hepatic metastasis models demonstrated that NETs promote release of high-mobility group box 1 (HMGB1), which activates Toll-like receptor 9 (TLR9) signalling in cancer cells." (PMID 41451221, 2025). "In our next experiment, we provided evidence for a close existing interplay between the TLR9-signaling and the autophagy response with remarkable influences on the tumor cell survival in HT29 colon cancer cells, subjected to intact or modified self-DNA treatments." (PMID 36359370, 2022). "In addition to CpG ODNs, a novel TLR9 agonist, IMO-2125, has also been shown to engage TLR9 leading to downstream immune signaling and suppression of A20 lymphoma and CT26 colon carcinoma tumor models in mice." (PMID 32508825, 2020).
colon carcinoma (continued). "However, the interrelated role of IGF1R inhibition and TLR9/autophagy signaling in HT29 colon cancer cells has not yet been clarified." (PMID 35651701, 2022). "However, the interrelated role of HGFR inhibition and TLR9/autophagy signaling in HT29 colon cancer cells has not yet been clarified." (PMID 35551547, 2022). "Thus the anti-apoptotic role of TLR9 agonist could protect the crypt cells from radiation-induced apoptotic death but does not affect the colon cancer cells, which undergoes cell death or senescence after radiation exposure." (PMID 22238604, 2012).
diffuse large B-cell lymphoma (19 papers, 2008 to 2025). "Growing evidence links the aggressiveness of non-Hodgkin’s lymphoma, especially the activated B cell-like type diffuse large B cell lymphomas (ABC-DLBCLs) to Toll-like receptor 9 (TLR9)/MyD88 and STAT3 transcription factor signaling." (PMID 29433938, 2018). "Besides that, TLR9 expression was significantly positively correlated with B cells in diffuse large B-cell lymphomas." (PMID 38537697, 2024). "Therefore, statistically significant, positive correlations with a signature found in TLR4, TLR9, and CD40 pathway activation were each associated with poor prognosis in diffuse large B cell lymphoma." (PMID 18937865, 2008). "NETs induced by tumor-derived CXCL8 coupled with CXCR2 promoted diffuse large B-cell lymphoma (DLBCL) progression by activating Toll-like receptor 9 (TLR9), an important DNA sensor, and its downstream pathways." (PMID 37198402, 2023). "Studies have shown that the formation of NETs in diffuse large B-cell lymphoma directly upregulates toll-like receptor 9 pathway, thereby activating the STAT3, NF-κB, and p38 pathways to facilitate tumor progression, which suggests that NETs might be a prognostic marker for tumors." (PMID 36034958, 2022). "In diffuse large B-cell lymphoma (DLBCL), NETs recruited via the IL8-CXCR2 axis activate TLR9, increasing NF-κB and p38 pathways and promoting tumor proliferation and growth." (PMID 38474175, 2024). "NETs have been found to be involved in the progression of diffuse large B-cell lymphoma (DLBCL) and colorectal cancer via TLR9-MAPK pathway." (PMID 34868992, 2021). "As previously reported, TLR9, in combination with BCR as well as mutant isoforms of MYD88, could result in sustained activity of NF-κB in the activated B-cell-like subtype of diffuse large B-cell lymphoma." (PMID 35707851, 2022). "During preparation for this manuscript, Staudt and colleague reported that MYD88, TLR9, and BCR complexes (My-T-BCR Complexes) exist in activated B-cell like diffuse large B-cell lymphoma and in WM, which might play a role in tumor growth and survival." (PMID 30402490, 2018).
glioblastoma (19 papers, 2013 to 2024). The most malignant astrocytic tumor (WHO grade IV). "Several clinical studies previously suggest that TLR9 may involving the pathogenesis of various types of cancer, where high expression of TLR9 in tumors is associated with decreased survival in patients with glioblastoma multiforme and esophageal cancer." (PMID 26087186, 2015). "CpG ODN shows promise as a potent immunotherapeutic drug against cancer, but specific cautions should be taken when activating TLR9, especially in the case of glioblastoma." (PMID 36611945, 2022). "Several reports have demonstrated a link between TLR9 expression in human glioblastoma multiforme tissues and patient follow-up." (PMID 36611945, 2022). "Additionally, increased TLR9 expression has been associated with the poor differentiation of cancer cells in breast, prostate and glioblastoma multiforme (GBM) tumors." (PMID 24959259, 2014). "In addition, an association of HIF-1α with TLR9 expression has been established in which HIF-1α siRNA decreases TLR9 transcripts in glioblastoma multiforme (GBM) cells treated with insulin-like growth factor 1 (IGF-1) under normoxic conditions." (PMID 38069210, 2023). "In addition to LPS, CpG oligodeoxynucleotides (CpG-ODN) binding to TLR9 have also been tested for the treatment of glioblastoma patients, but data indicate that only some glioblastoma multiforme patients might benefit from this therapy." (PMID 26863029, 2016). "Previous clinical studies similarly suggest that TLR9 may contribute to the pathogenesis of various types of cancer, where high expression of TLR9 in tumors has been shown to predict decreased survival in patients with glioblastoma multiforme and esophageal cancer." (PMID 23761830, 2013). "Additionally, a phase II study (NCT00190424) attempted to deliver a TLR9 agonist (oligodeoxynucleotides containing CpG motifs, CpG-ODN) to the brain to treat recurrent glioblastoma; disappointingly, this strategy was proved ineffective." (PMID 36311702, 2022). "Furthermore, oligodeoxynucleotides that act on Toll signaling by binding to intracellular Toll-like receptor 9 (TLR9) and thus activate innate and adaptive immunity at first showed no improvement of overall survival of glioblastoma patients, but are being further investigated." (PMID 30871102, 2019).
pneumonia (19 papers, 2010 to 2025). An acute, acute and chronic, or chronic inflammation focally or diffusely affecting the lung parenchyma, caused by an infection in one or both of the lungs (by bacteria, viruses, fungi, or mycoplasma.). "In this work, we demonstrated that pneumonia caused by experimental infection with C. gattii was more severe in C57BL/6 TLR9-/- mice than C57BL/6 WT mice." (PMID 36145419, 2022). "The aged mice also express lower levels of TLR1, TLR6, and TLR9 in the lungs, which also increases their susceptibility to pneumonia." (PMID 32849610, 2020). "Similarly, TLR9 deficiency increased mortality upon intranasal pneumococcal challenge in a murine pneumonia model." (PMID 33531028, 2021). "For example, it was shown that intratracheal administration of mtDNA in rats provoked the development of pneumonia via the TLR9-p38 MAPK signaling pathway." (PMID 34181353, 2021). "Data obtained in other infection models indicate that TLR9 can be activated by bacterial and host DNA released into the airways during pneumonia, as well as by intracellular bacteria and DNA of mitochondrial origin released to the cytosol upon infection." (PMID 30452654, 2019). "TLR9-controlled signalling is also required for protective immunity against Klebsiella-induced pneumonia." (PMID 30452654, 2019). "Our findings would help design future therapeutic strategies, based on TLR9 inhibition, to control P. aeruginosa-induced pneumonia." (PMID 24595157, 2014). "By comparison, defects in later production (24 hrs) of IL-12 and expression of the activating cytokine IFN-γ was observed in TLR9 deficient mice after bacterial challenge, consistent with the notion the TLR9 promotes type 1 immunity during pneumonia." (PMID 20360853, 2010). "In Baladi goats with pneumonia and healthy control group, PCR-DNA sequencing revealed SNPs linked to pneumonia susceptibility and resistance in immunological genes (SLC11A1, CD-14, CCL2, TLR1, TLR7, TLR8, TLR9, defensin, SP110, SPP1, BP1, A2M, ADORA3, CARD15, IRF3, and SCART1)." (PMID 40221769, 2025). "Here, we report previously unknown, TLR9-independent immunometabolic modulation by ODN that results in generation of pneumonia-protective mtROS." (PMID 37695784, 2023). "Furthermore, in murine pneumonia TLR9-mediated DCs and macrophage responses effectively cleared the bacteria from the lungs." (PMID 28052108, 2017). "Moreover, we found that TLR4 and TLR9 regulate lung IL-23 and IL-17 responses in pneumonia." (PMID 20360853, 2010). "The immune genes’ mRNA levels in goats (SLC11A1, CD-14, CCL2, TLR1, TLR7, TLR8, TLR9, defensin, SP110, SPP1, BP1, A2M, ADORA3, CARD15, IRF3, and SCART1) varied between the healthy and infected goats with pneumonia." (PMID 40711280, 2025). "In mice pneumonia studies, TLR2, TLR5 and TLR9 were required for effective innate immune responses against L. pneumophila." (PMID 20615218, 2010). "ODN protection requires both TLR9 and RIG-I pneumonia-protective signaling." (PMID 39352770, 2024). "During pneumonia, AECs recognize various pathogens due to the expression of different PRRs, including TLRs [TLR1, TLR2, TLR4, TLR5, TLR6 (Extracellular TLRs), and TLR3, TLR7, TLR8, and TLR9 (Intracellular TLRs)] and NLRs comprising inflammasome." (PMID 32849610, 2020). "Through PCR-DNA sequencing in Baladi goats with and without pneumonia, SNPs linked to pneumonia susceptibility and resistance were discovered in the immunological (SLC11A1, CD-14, CCL2, TLR1, TLR7, TLR8, TLR9, defensin, SP110, SPP1, BP1, A2M, ADORA3, CARD15, IRF3, and SCART1) genes." (PMID 40711280, 2025). "Leveraging these defensive mechanisms, we identified a pneumonia-protective, synthetic PAMP-based therapeutic comprising a diacylated lipopeptide ligand for TLR2/6 (Pam2CSK4 [Pam2]) and a class C unmethylated cytosine-guanine (CpG) oligodeoxynucleotide ligand for TLR9 (ODN M362 [ODN]." (PMID 39352770, 2024).
pneumonia (continued). "However, in a mouse model of pneumonia, TLR9 exhibited a protective effect against the Gram-negative bacterium, Klebsiella pneumonia." (PMID 24595157, 2014). "The levels of immunological genes (SLC11A1, CD-14, CCL2, TLR1, TLR7, TLR8, TLR9, defensin, SP110, SPP1, BP1, A2M, ADORA3, CARD15, IRF3, and SCART1) vary in goats with and without pneumonia." (PMID 40221769, 2025). "Real-time PCR was conducted to quantify the expression levels of immunological markers (SLC11A1, CD-14, CCL2, TLR1, TLR7, TLR8, TLR9, β defensin, SP110, SPP1, BP1, A2M, ADORA3, CARD15, IRF3, and SCART1) in Baladi goats with and without pneumonia resistance." (PMID 36977224, 2023). "While single-ligand ODN treatment significantly improved pseudomonal pneumonia survival of Tlr9–/–, Rigi–/–, and Mavs–/– mice, the same ODN treatment did not induce significant protection against pseudomonal pneumonia in Tlr9–/–;Mavs–/– or MyD88–/–;Mavs–/– double-knockout mice." (PMID 39352770, 2024).